MYD88 (MYD88 innate immune signal transduction adaptor)
Diseases named in the same sentence as MYD88 in open-access papers (continued):
Sharing a sentence is not in itself a finding about the gene and the disease.
diffuse large B-cell lymphoma (continued). "For example, MYD88-L265P encoding mutations are known to occur in a fraction of the activated B cell (ABC) diffuse large B-cell lymphomas (DLBCL), in the vast majority of LPL, and in rare MZL, with differences based on the primary anatomical site." (PMID 36675328, 2023). "Recently, it was shown that extracellular vesicles secreted by a diffuse large B-cell lymphoma (DLBCL) contain the mutated form of myeloid differentiation primary response 88 (MYD88), a part of reprogramming the bone marrow lymphoid microenvironment." (PMID 33114418, 2020). "The most malignant subtype of diffuse large B-cell lymphoma (DLBCL) is associated with gain-of-function mutation in MyD88 (L265P)." (PMID 31695691, 2019). "MYD88 somatic variants have been also observed in other B-cell lymphoproliferaive disorders, including chronic lymphocytic leukemia and activated B-cell-like subtype of diffuse large B-cell lymphoma (ABC-DLBCL), occurring in about 3% and 29% of the cases, respectively." (PMID 28423722, 2017). "Recently, many investigators have reported that the prevalence of MYD88 L265P mutation ranges from 0% to 94% in different series of diffuse large B-cell lymphoma (DLBCL) patients." (PMID 28496180, 2017). "Recently, mutations in MyD88 that cause the constitutive activation of the MyD88 signalling pathway have been identified as a major cause of the activated B-cell subtype of DLBCL (diffuse large B-cell lymphoma), one of the least curable forms of this blood cancer." (PMID 23441730, 2013). "In diffuse large-B-cell lymphoma (DLBCL), ctDNA facilitates non-invasive genotyping by identifying hallmark mutations (e.g., MYD88, CD79B, EZH2), enabling molecular cluster classification." (PMID 40430009, 2025). "Research has shown that patients with wild-type MYD88 have a more aggressive disease course, resembling that of diffuse large B-cell lymphoma." (PMID 40351903, 2025). "Diffuse large B cell lymphoma (DLBCL), the most common and aggressive form of non-Hodgkin lymphoma, often exhibits multiple genomic aberrations, including mutations in the MYD88 and CD79B genes." (PMID 39868594, 2025). "HSPH1 stimulates NF-κB signaling through MyD88 stabilization in activated B cell diffuse large B cell lymphoma." (PMID 38932372, 2024). "For instance, in diffuse large B-cell lymphoma (DLBCL) and multiple myeloma (MM), proteins such as CD79 and MyD88 trigger NFκB activation through gain-of-function mutations." (PMID 38331871, 2024). "A somatic L265P mutation within the Toll/interleukin-1 receptor (TIR) domain of MYD88 is found in 90% of Waldenström macroglobulinemia cases and in a significant subset of diffuse large B-cell lymphomas." (PMID 37591861, 2023). "The result showed 23 gene mutations, including MYD88, CD79B, CDKN2A, PIM1, RELN, PCLO, CREBBP, and so on, supporting the diagnosis of diffuse large B-cell lymphoma." (PMID 36599976, 2023). "In activated B cell-like diffuse large B cell lymphoma (ABC-DLBCL), IRAK1 overexpression contributes to DLBCL aggressiveness in patients with MyD88 gain-of-function mutation." (PMID 37370720, 2023). "The genetic test results of the left frontal parietal lobe lesion result revealed 23 gene mutations, including MYD88, CD79B, CDKN2A, PIM1, RELN, PCLO, CREBBP, and so on, supporting the diagnosis of diffuse large B-cell lymphoma." (PMID 36599976, 2023). "In the literature, MYD88 and CD79B mutations have been reported in 27/46 (58.7%) and 11/33 (33.3%) primary breast diffuse large B cell lymphomas in females." (PMID 37884941, 2023). "Indeed, MYD88 mutations are also found in 30% of activated B-cell type diffuse large B-cell lymphomas (ABC-DLBCL), more than half of primary cutaneous DLBCLs, leg type, and many DLBCLs at immune-privileged sites but not in plasma cell myelomas, even IgM types." (PMID 34017329, 2021).
diffuse large B-cell lymphoma (continued). "Mutations in MYD88 have been studied extensively in lymphoplasmacytic lymphoma/Waldenstrom macroglobulinemia (LPL/WM) and diffuse large B-cell lymphoma (DLBCL), due to the relatively high frequency of MYD88 mutations in these neoplasms." (PMID 32848129, 2020). "Review of our genetic data on diffuse large B cell lymphoma (DLBCL) and Waldenstrom macroglobulinemia (WM), found that a large percentage of DLBCL and WM cases that have a MYD88 mutation also harbor a TNFAIP3 loss, 55% DLBCL and 28% of WM, respectively." (PMID 30301877, 2018). "Growing evidence links the aggressiveness of non-Hodgkin’s lymphoma, especially the activated B cell-like type diffuse large B cell lymphomas (ABC-DLBCLs) to Toll-like receptor 9 (TLR9)/MyD88 and STAT3 transcription factor signaling." (PMID 29433938, 2018). "Expression of the TLR adaptor protein MyD88 has been associated with a more aggressive hepatocellular carcinoma (HCC) phenotype in humans, and activating mutations have been found in diffuse large B-cell lymphoma." (PMID 25846753, 2015). "As previously reported, TLR9, in combination with BCR as well as mutant isoforms of MYD88, could result in sustained activity of NF-κB in the activated B-cell-like subtype of diffuse large B-cell lymphoma." (PMID 35707851, 2022). "As an example in lymphoma, this technique has a potential clinical use in diffuse large B cell lymphoma (DLBCL), as co-occurring mutations in MYD88 and CD79B can predict response to Ibrutinib treatment, thus providing a predictive molecular tool for patient and therapy selection." (PMID 34205827, 2021). "In MM, MYD88 serves as an adapter protein for TLRs and an activator of NF-κB signaling that is not due to MYD88 mutation, as in diffuse large B cell lymphoma and Waldenström’s macroglobulinemia; in our study, we observed its upregulation only in PBs of both premalignant and active MM stages." (PMID 36752202, 2023). "In diffuse large B-cell lymphoma (DLBCL), EZH2 and GNA13 variants are observed exclusively in the germinal center B-cell subtype, whereas CARD11, MYD88, and CD79B variants are characteristic of the activated B-cell subtype." (PMID 37601650, 2023). "There is also evidence of cross-communication with the BCR pathway triggered by mutated MyD88 through the activation of the BCR-signaling component SYK (spleen tyrosine kinase) in WM and activated B-cell diffuse large B-cell lymphoma (ABC DLBCL) cells." (PMID 35628381, 2022). "In the activated B-cell-like (ABC) subtype of diffuse large B-cell lymphoma (DLBCL), MyD88 L265P is reported to contribute to the constitutive NF-κB and JAK kinase signaling, which promotes malignant cell survival in these lymphomas." (PMID 35309296, 2022). "A recent study found that A20 expression prevents diffuse large B-cell lymphoma (DLBCL) cell proliferation and migration by inducing TLR4/MyD88/NF-κB pathway-mediated autophagy in vitro." (PMID 40214497, 2025). "The detection of a MyD88 mutation is a key indicator for diagnosing B-cell lymphomas, including primary vitreoretinal lymphoma (PVRL), central nervous system diffuse large B-cell lymphoma (CNS DLBCL), or other forms of B-cell lymphoma." (PMID 39559629, 2024). "ST2825 is a synthetic peptidomimetic compound that has been found to inhibit MyD88-dependent inflammatory signalling pathways and could have therapeutic potential for conditions such as systemic lupus erythematosus, traumatic brain injury and diffuse large B-cell lymphoma." (PMID 38416868, 2024). "For instance, in activated B cell diffuse large B cell lymphoma (ABC-DLBCL), HSP110 promotes the proliferation of ABC-DLBCL cell lines by enhancing MyD88-mediated NF-κB activity." (PMID 35986277, 2022).
diffuse large B-cell lymphoma (continued). "In cases of diffuse large B-cell lymphoma (DLBCL), immunopositivity of MYD88 is associated with non-germinal center B-cell origin (P < .001)." (PMID 38335426, 2024). "VRL, as well as PCNSL, display typically an activated B cell-like (ABC) phenotype of diffuse large B-cell lymphoma (DLBCL), with frequent CD79B and MYD88 mutations, which may represent a strong biological rationale for the use of BTK inhibitors in the treatment of PCNSL and VRL." (PMID 33968786, 2021). "During preparation for this manuscript, Staudt and colleague reported that MYD88, TLR9, and BCR complexes (My-T-BCR Complexes) exist in activated B-cell like diffuse large B-cell lymphoma and in WM, which might play a role in tumor growth and survival." (PMID 30402490, 2018).
diabetes (76 papers, 2009 to 2026). "Pathological immune responses via the TLR4/MyD88/NF-κB pathway and the IL-17/IL-23 axis were also linked to liver fibrosis in diabetes." (PMID 40362271, 2025). "Transplanting fecal samples from diabetes-protected MyD88-deficient NOD mice to wild type female NOD/LtJ mice led to a delayed onset of diabetes and a reduced insulitis." (PMID 35242797, 2022). "Both male and female MyD88-deficient NOD mice were protected from diabetes but only when gut microbiota were present." (PMID 33322152, 2020). "Here we show that myeloid cell-specific MyD88 deficiency considerably protected mice from the development of streptozotocin (STZ)-induced diabetes." (PMID 29522531, 2018). "Specifically for T1D, MyD88 deficiency completely prevented diabetes development in NOD mice in a microbiota-dependent manner." (PMID 29522531, 2018). "NOD mice in which the response to the microbiome is limited due to a deficiency in the Toll-like receptor adaptor protein MyD88, exhibit reduced β cell-specific Teff reactivity and diabetes incidence." (PMID 29312356, 2017). "It has been found that TLR2, TLR3, and TLR4 are dispensable for development of T1D when individually deleted, in contrast to the effect of complete protection from diabetes associated with loss of MyD88." (PMID 26347203, 2015). "Gut homeostasis is directly linked to diabetes in NOD mice as MyD88-deficient mice only develop diabetes in germ-free conditions." (PMID 22558306, 2012). "Another possibility is that MyD88 deficiency favors a significant change in the composition of the commensal flora or the development of infections that both inhibit diabetes onset." (PMID 20628601, 2010). "From these observations, we are next interested in investigating mechanisms of diabetes observed in MyD88-deficiency." (PMID 20824098, 2010). "In order to study if exogenous or endogenous pathogens (intestinal commensal bacteria) modulate OVA-induced allergic asthma or diabetes, we studied the effect of MyD88 deficiency on these diseases." (PMID 20628601, 2010). "Hesperetin has demonstrated its ability to modulate inflammatory cytokine release, NF-κB acetylation, and SIRT 3/6 expression through the TLR/MyD88/NF-κB signaling pathways, suggesting its promise as a treatment option for averting diabetes and its associated complications." (PMID 38234970, 2023). "Interestingly, when MyD88 deficiency was generated in germ-free mouse, the diabetes rate was similar to wild-type NOD mouse." (PMID 36059452, 2022). "MyD88 deficiency protected the NOD mouse almost completely from diabetes by 30 weeks of age." (PMID 36059452, 2022). "We hypothesized that MyD88 or TRIF deficiency in myeloid cells may exert opposing effects on the development of STZ-induced diabetes by differentially regulating the responses of antigen presenting cells to apoptotic beta-cells." (PMID 29522531, 2018). "Collectively, these results showed that MyD88 deficiency in myeloid cells considerably inhibited the development of diabetes in mice treated with STZ, suggesting that MyD88 signaling in myeloid cells promotes autoimmune responses leading to the development of T1D." (PMID 29522531, 2018). "At present, it is unknown whether MyD88-deficient human subjects are prone to diabetes and it will be an open questions." (PMID 20824098, 2010). "We found that MyD88-deficient mice fed with high fat diet develop severe diabetes." (PMID 20824098, 2010). "In addition, it will be needed to investigate what type of cell is responsible for diabetes observed in MyD88-deficiency." (PMID 20824098, 2010). "Then, what is the responsible factor exacerbating diabetes in MyD88 deficiency?" (PMID 20824098, 2010). "This study investigated the role of MyD88/IL-10 signaling in diabetes-induced systemic inflammation and hepatic gluconeogenesis." (PMID 41898743, 2026).
diabetes (continued). "Myeloid differentiation primary response gene 88 (MyD88) is an important immunoregulatory factor, and studies have found that inhibiting MyD88 has a good effect on diabetes." (PMID 38026969, 2023). "In summary, we have shown that diabetes increases the interaction between MyD88 and TLR4 to initiate inflammatory injury in cardiomyocytes." (PMID 36180407, 2022). "Intestinal barrier defenses and MyD88 are impaired in diabetes and ICAM and FMO3 expression induced while AhR ligands reverse diabetes-induced intestinal barrier damage, insulin insensitivity, FMO3/ICAM expression and systemic inflammation." (PMID 35966699, 2022). "These demonstrate that the transfer of gut microbiota from diabetes-protected MyD88-deficient NOD mice can reduce insulitis and significantly delay the onset of diabetes." (PMID 34805250, 2021). "Studies have shown that resveratrol can protect the cardiovascular tissues of rats with CHD and diabetes by downregulating the TLR4/MyD88/NF-κB signalling pathway." (PMID 34887932, 2021). "To date, only few studies correlated NLRP3 and MyD88 with hyperglycemia damages, like diabetes-induced endothelial inflammation and atherosclerosis." (PMID 33096896, 2020). "The knock out (KO) of myeloid differentiation primary response 88 (Myd88) (an adapter protein downstream of multiple TLR involved in sensing of microorganisms) in the NOD mouse protected against diabetes." (PMID 30931309, 2019). "This means that dysbiosis of gut microbiota in MyD88−/−NOD mice resulted in protection from diabetes development." (PMID 29673211, 2018). "Due to LTB4 amplification of MyD88-dependent responses, we suggest that cytokine production in diabetes occurs in response to the activation of receptors that use MyD88 as an adaptor molecule to activate the NFκB pathway, the TLR family." (PMID 30242286, 2018). "The protective effect of myeloid-specific MyD88 deficiency in NOD mice was transient, manifesting with significant delay in the development of diabetes, but the mice eventually developed the disease." (PMID 29522531, 2018). "Taken together, these results showed that myeloid cell specific MyD88 signaling contributes to the development of diabetes in NOD mice by accelerating the onset of the disease." (PMID 29522531, 2018). "Strikingly, diabetes is prevented in NOD mice housed under germ-free conditions and inoculated with microbiota derived from MyD88-deficient animals, demonstrating that the microbiota also has a protective role in T1D." (PMID 29312356, 2017). "We reported that inducible intestinal epithelial cell-specific deletion of MyD88 partially protects against diet-induced fat storage, inflammation and diabetes via mechanisms directly involving the gut microbiota." (PMID 25476696, 2014). "We postulate that MyD88 is novel target to inhibit early abnormalities of diabetic retinopathy and perhaps other complications of diabetes." (PMID 23874797, 2013). "This diabetes-induced increase in retinal superoxide production was totally inhibited by deleting either MyD88 or IL-1ßr from bone marrow-derived cells only." (PMID 23874797, 2013). "We found that diabetic, but not normal retinas, were stimulated by Pam3CysK, which activates the TLR2/MyD88 pathway, and supports the concept that this pathway is up-regulated in the retina in diabetes." (PMID 23874797, 2013). "Our findings would provide a molecular basis for understanding diabetes and developing a novel pharmacological treatment targeting MyD88." (PMID 20824098, 2010). "We also examined the effect of the genetic invalidation of MyD88 on the development of spontaneous diabetes, as previously performed by the group of A. Chervonsky and additionally in the allergic asthma model." (PMID 20628601, 2010). "The present results indicate an unanticipated important link between MyD88 and the development of diabetes mellitus." (PMID 20824098, 2010).